SMAD3 (SMAD family member 3)
Diseases named in the same sentence as SMAD3 in open-access papers (continued):
Sharing a sentence is not in itself a finding about the gene and the disease.
Glucose intolerance (4 papers, 2020 to 2025). Glucose intolerance (GI) can be defined as dysglycemia that comprises both prediabetes and diabetes. "HFD-fed Gdf15−/− mice displayed aggravated glucose intolerance compared to HFD-fed WT mice, with increased levels of SMAD3 and PAI-1 in the skeletal muscle." (PMID 39825925, 2025).
infarction (4 papers, 2022 to 2024). A localised pathological necrosis of tissue resulting from obstruction of the blood supply usually by a thrombus, an embolus, or vascular torsion. "Myofibroblast-specific Smad3 protects from cardiac rupture in the non-reperfused infarction model and attenuates chamber dilation." (PMID 35563692, 2022).
kidney injury (4 papers, 2021 to 2025). Trauma to the kidney. "D. opposita, contains dioscin, which down-regulates TGF-β1 and phosphorylated Smad3 (p-Smad3), and up-regulates Smad7 in a fructose-induced kidney injury model, exerting anti-fibrotic effects." (PMID 41459479, 2025).
medulloblastoma (4 papers, 2014 to 2021). A malignant, invasive embryonal neoplasm arising from the cerebellum. "Determining to what extent high AHRR expression in human SHH medulloblastoma is associated with elevated TGFβ-SMAD3 signalling will be an important next step to identify patients that may benefit from TGFβ-SMAD3 inhibition and/or AHR agonist therapies." (PMID 31924815, 2020). "We identify a specific role for AHR in regulating the TGFβ-SMAD3 signalling axis in CPCs from these tumours and identify a new role for TGFβ-SMAD3 activity in medulloblastoma CPC differentiation." (PMID 31924815, 2020). "Taken together, these studies suggested that Ahr deletion in SHH medulloblastoma promoted CPC fate via induction of TGFβ/SMAD3 signalling." (PMID 31924815, 2020). "Together, these findings implicated the TGF-β/SMAD3 pathway in mediating the effect of AHR signalling on proliferation and cell survival of medulloblastoma CPCs." (PMID 31924815, 2020). "Immunostaining of these cells revealed that all Ahr-deficient medulloblastoma CPCs were strongly positive for p-SMAD3, compared to control culture that did not display SMAD3 activation." (PMID 31924815, 2020). "We propose that TGFβ/SMAD3 inhibition may represent an actionable therapeutic approach for a subset of aggressive SHH medulloblastomas characterised by reduced AHR pathway activity." (PMID 31924815, 2020). "Next, we asked whether AHR also inhibited SMAD3 activation in SHH medulloblastoma." (PMID 31924815, 2020). "This study only assessed SHH medulloblastomas from 35 patients and using nuclear localisation of SMAD3 as a read-out of pathway activation may not be ideal." (PMID 31924815, 2020).
nasal polyps (4 papers, 2020 to 2025). "The hypoxia‐induced EMT process has been shown to contribute to nasal polyposis in CRSwNP, mediated by HIF‐1α and phosphorylated Smad3 (pSmad3), leading to a loss of E‐cadherin and induction of α‐SMA." (PMID 40176272, 2025). "To further analyze the effects of OSM and IL-4 on nasal-polyp-derived fibroblasts at the cell signaling level, we studied their potential impact on Smad3 nuclear translocation induced by TGF-β1." (PMID 35682987, 2022). "Similarly, TGFβ1 induces EMT in epithelial cells derived from nasal polyps or the inferior turbinate, with this effect being particularly pronounced in tissues with high levels of TGFβ1 and Smad3 compared to healthy tissue samples, consistent with our findings." (PMID 39338148, 2024). "When fibroblasts from nasal polyps were treated with TGF-β1, the nuclear translocation of Smad3 was increased compared to the control." (PMID 35682987, 2022). "Epithelial cells of nasal polyps show an abnormal expression α-SMA and when they were cultivated in hypoxia conditions, EMT was induced via a SMAD3-dependent mechanism suggesting the crucial role for EMT in the pathogenesis of nasal polyps." (PMID 32961745, 2020).
oral cancer (4 papers, 2021 to 2026). "Hence, it suggests that SMAD3, MMP3, SERPINE1, and THBS1 serve as tumor promoters in oral cancer." (PMID 36033831, 2022).
pancreatic adenocarcinoma (4 papers, 2014 to 2021). "In the current work, we explored the role of the TGFβ-SMAD3 signaling pathway in pancreatic stellate cells and the consequences for tumor-stroma interactions and pancreatic adenocarcinoma cell migratory activity." (PMID 27473228, 2016). "By using mCherry cell signaling reporter lines, the authors observed dysregulated activity of the Notch pathway during the early stages and dysregulation of Smad3/TGFβ and Shh pathways during the later stages of pancreatic adenocarcinoma." (PMID 24878567, 2014). "We next investigated the role of the Smad3/TGFβ signaling pathway by analyzing a specific mCherry reporter driven by Smad3 responsive elements; Smad3 is reported to be activated in pancreatic adenocarcinoma as a response to the antiproliferating function of TGFβ." (PMID 24878567, 2014). "Based on the TCGA database results, the expression levels of CREB1, PTEN, SMAD3, and CASP3 genes are up-regulated in the pancreatic adenocarcinoma." (PMID 34155232, 2021). "Furthermore, the expression of FAM83A was strongly associated with the levels of p-Smad3 (P<0.001) and nuclear β-catenin (P<0.001), indicators of TGF-β/Smad and Wnt/β-catenin pathway activation, respectively, in 103 paraffin-embedded pancreatic adenocarcinoma samples." (PMID 28287611, 2017). "Later, using TCGA data, we realized that the expression of PTEN, CREB1, CASP3, and SMAD3 are significantly (|Log FC| ≥ 1 and p value < 0.01 as the cut-off criteria) increased in Pancreatic adenocarcinoma (PAAD) (data not shown)." (PMID 34155232, 2021).
papillary thyroid carcinoma (4 papers, 2021). "MKL1 recruits Smad3 to transactivate MMP2 in papillary thyroid cancer, consequently accelerating nodal metastasis." (PMID 33500406, 2021). "Moreover, curcumin was demonstrated to inhibit metastasis in human papillary thyroid carcinoma cells by downregulating components of the prometastatic signaling pathway TGFB1/SMAD2/SMAD3." (PMID 34422220, 2021).
pituitary adenomas (4 papers, 2014 to 2024). "Our group also previously showed that menin, a potent tumor suppressor, specifically interacts with Smad3 to mediate TGFβ anti-proliferative responses in pituitary adenoma." (PMID 38201651, 2024). "miR-582-5p has been shown to be over-expressed in pituitary adenomas, and is predicted to target Smad-3, but is otherwise unstudied." (PMID 24805821, 2014).
prostate tumor (4 papers, 2014 to 2025). "Furthermore, SMAD3 and SMAD4 were also downregulated in human prostate tumors being positive for ETV1 gene fusions." (PMID 31160676, 2019). "In particular, we found primarily overexpression of CTNNB1, CDH1, SMAD2, SMAD3, TCF3, LEF1 in younger patients and overexpression of SNAI1 and underexpression of KRT5, KRT19, OCLN, CDH2 and MUC1 which clearly indicates different characteristics of prostate tumor in younger vs older patients." (PMID 29206234, 2017).
silicosis (4 papers, 2016 to 2026). Silicosis is a respiratory disease caused by breathing in (inhaling) silica dust. "In summary, CHRF may exacerbate inflammation and fibrosis associated with silicosis through the miR-489/MyD88/Smad3 pathway." (PMID 40612103, 2025). "In non-small cell lung cancer and silicosis, CHRF exacerbates inflammation and fibrosis via the miR-489/MyD88/Smad3 axis." (PMID 40612103, 2025). "The results indicated that the expression of SMAD2, MAPK3, THBS1, ITGB3, and BMP4 was increased, while the expression of SMAD3 and CD44 was significantly low expression in PBMCs from patients with silicosis, indicating consistent results with the RNA-Seq data." (PMID 34517882, 2021).
type 2 diabetic nephropathy (4 papers, 2014 to 2024). "Smad3 deficiency prevents the development of type 2 diabetic nephropathy; however, the underlying molecular mechanisms remain unknown." (PMID 33369170, 2021).
aortic valve disease (3 papers, 2022 to 2023). "We report a middle-aged female, heterozygous for the R18W novel variant of the SMAD3 gene, with a history of an aortic valve disorder and three aortic valve replacements in a span of 15 years." (PMID 37252476, 2023).
arteriopathies (3 papers, 2014 to 2020). "In SMAD3 mutation carriers, arterial disease is centered by TAA as an established predominant and life-threatening manifestation, observed in 72% of our patients (36/50)." (PMID 24804794, 2014). "The 2 patients with SMAD3 variants, which also causes LDS) have not yet been screened for remote arteriopathies." (PMID 33125268, 2020).
autosomal dominant polycystic kidney disease (3 papers, 2023 to 2025). Autosomal dominant form of polycystic kidney disease. "Of note, recent multimodal single nuclear RNA and ATAC sequencing studies in patients with autosomal dominant polycystic kidney disease identified a TGFβ/SMAD3 signature across a number of cell types, including within cystic epithelial cells." (PMID 37703354, 2023).
B-cell lymphoma (3 papers, 2021 to 2025). "Extensive analysis of the transcriptional regulation of AICDA in a murine mature B-cell lymphoma cell line had revealed that CD40L, IL-4, and TGFβ induce AICDA expression via NF-κB, Stat6 and Smad3/4 signaling, respectively." (PMID 33507341, 2021). "In 2001, SMAD3 and its homolog, SMAD4, have been shown to mediate the expression of autoimmune antibodies during B-cell lymphoma." (PMID 34899868, 2021).
bronchopulmonary dysplasia (3 papers, 2019 to 2023). Bronchopulmonary dysplasia is a chronic respiratory disease that results from complications related to lung injury during the treatment of infant acute respiratory distress syndrome in low-birth-weight premature infants or from abnormal lung development in older infants. "In a rat model of bronchopulmonary dysplasia (BPD), montelukast treatment inhibited the expression of hyperoxia-induced mesenchymal markers, such as collagen I (Col I), metalloproteinase-1 (MMP-1), MMP-3, TGF-β1, and Smad3, in lung tissues by inactivating the TGF-β1/Smad signaling pathway." (PMID 35517780, 2022).
cerebral infarction (3 papers, 2022 to 2024). An ischemic condition of the brain, producing a persistent focal neurological deficit in the area of distribution of the cerebral arteries. "SMAD3 genetic locus variants associated with higher blood levels of this gene and with lower frequency of brain infarcts." (PMID 38902234, 2024). "In summary, our antemortem analyses revealed associations of SMAD3 locus genetic variants with both higher blood SMAD3 levels and lower brain infarcts." (PMID 38902234, 2024). "In antemortem studies, we demonstrated associations of SMAD3 locus genetic variants with both higher blood levels of this gene and lower frequency of brain infarcts, as well as correlations of high blood SMAD3 with lower brain amyloid β and less cortical atrophy." (PMID 38902234, 2024). "The precise mechanism of the neuroprotective effect of miRNA-323 remains unclear, but it may regulate apoptosis during cerebral infarction by targeting the TGF β1/SMAD3 signaling pathway or by modulating BRI3, which is involved in I/R injury-induced neuronal apoptosis." (PMID 37763638, 2023). "1,25-D3 reduced cerebral infarction volume, increased the recovery of CBF and expressions of VDR, TGF-β, p-Smad2, p-Smad3, and VEGF, significantly increased IB4+ tip cells and CD31+ vascular length in the peri-infarct area compared with the DMSO group." (PMID 35369317, 2022). "Few studies have shown that miR-323-5p controls apoptosis in cerebral infarction conditions by modulating the transforming growth factor-β1 (TGF-β1)/Smad3 signaling pathway or BRI3, but no studies have been conducted regarding the mechanisms associated with DEX." (PMID 37763638, 2023).
Chronic colitis (3 papers, 2010 to 2026). A chronic inflammatory disease of the large intestine (colon, cecum and rectum). "As the main profibrotic transcription factors, SMAD2 and SMAD3 were activated in DSS-induced chronic colitis, and the increased phosphorylation levels of SMAD2 and SMAD3 were reversed by ME treatment." (PMID 34456904, 2021). "For instance, in a chronic colitis mouse model, metformin reduced TGF-β1 expression and Smad3 phosphorylation, mitigating inflammation and fibrosis." (PMID 41578026, 2026). "In wt mice with chronic colitis, IL-23a, IL-13, NF-kB2, PTGS1, SMAD3 and SMAD7 (P≤0.05) were significantly down-regulated, with the largest variations affecting the expression of IL-23a and IL-13 (100- and 10-fold)." (PMID 20706593, 2010).
cyst (3 papers, 2021 to 2024). A sac-like closed membranous structure that may be empty or contain fluid or amorphous material. "Last, we took a pathway-agnostic approach to examine how TGFβ-SMAD3 regulates cyst formation in PCLD." (PMID 37703354, 2023). "SMAD3 inhibition did not reduce the number of panCK-positive cysts in the Wdr35-/- liver; however, it reduced cyst size." (PMID 37703354, 2023).
disc degeneration (3 papers, 2016 to 2023). "Further supporting the role of altered TGFβ signaling in disc degeneration, patients with mutations in the gene encoding SMAD3 resulting in increased Smad3 phosphorylation showed disc degeneration beginning as early as 12 years of age45." (PMID 35474298, 2022). "Additionally, patients harboring activating Smad3 mutations exhibited increased Smad3 phosphorylation levels coupled with disc degeneration beginning as early as 12 years of age." (PMID 27019229, 2016). "The molecular mechanism by which CILP promotes disc degeneration is significantly related to its inhibitory function of the TGF‐β/Smad3 pathway, which is critical in maintaining the natural metabolism of the NP matrix." (PMID 38023721, 2023).
Duchenne muscular dystrophy (3 papers, 2018 to 2024). Duchenne muscular dystrophy (DMD) is a neuromuscular disease characterized by rapidly progressive muscle weakness and wasting due to degeneration of skeletal, smooth and cardiac muscle. "Therefore, the goal of targeting the MH2 domain of SMAD3 was to impede the fibrosis process associated with Duchenne muscular dystrophy (DMD)." (PMID 39415830, 2024). "Here, authors show that Smad3 acetylation via HDAC6 inhibition reverses Duchenne muscular dystrophy-like symptoms in the mdx mouse model, suggesting a potential therapeutic target for the disorder." (PMID 36402791, 2022).
ductal adenocarcinoma (3 papers, 2011 to 2021). "Through analysis of patient derived breast tissues and mouse models of DCIS, we showed that expression of CCL2, CCR2, phospho-SMAD3 and phospho-p42/44MAPK proteins were associated with invasive breast ductal carcinomas." (PMID 33888841, 2021). "Inhibiting the function of endogenous Smad3 in ductal adenocarcinoma, liver and human lens cell lines significantly suppresses the effect of TGFβ on cell proliferation." (PMID 25891822, 2015). "Nevertheless the abnormally high levels of germline expression as well as statistically significant over-expression of SMAD3 in invasive ductal carcinoma (IDC) compared to normal tissues raises the possibility that epistatic interactions of SMAD3 may contribute to the oncogenic activities of TGF-ß." (PMID 21835029, 2011).
dyslipidemia (3 papers, 2012 to 2025). "Compared to Smad3 wild-type (WT)-db/db mice, Smad3 KO-db/db mice were protected against dyslipidemia and NAFLD." (PMID 37511155, 2023). "Mechanistically, we uncovered that Smad3 targeted peroxisome proliferator-activated receptor delta (PPARδ) to induce dyslipidemia and NAFLD in db/db mice, which was improved by genetically deleting and pharmacologically inhibiting Smad3." (PMID 37511155, 2023).
fibrosarcoma (3 papers, 2013 to 2022). A malignant mesenchymal fibroblastic neoplasm affecting the soft tissue and bone. "Among the few factors, TGFβ has been shown to induce HDAC6 activity through Smad3 activation in lung epithelial cells and we showed here that stimulation of fibrosarcoma cells with TGFβ enhanced HDAC6 activity." (PMID 23405166, 2013). "In this study, we showed that exposure of fibrosarcoma cells to hypoxia promoted HDAC6 tubulin deacetylase activity that orchestrated Smad3 activation and nuclear translocation." (PMID 23405166, 2013). "We have previously shown that hypoxia increases the cellular level and the nuclear accumulation of phospho-SMAD3 (pSMAD3) without affecting total SMAD3 levels in HT-1080 human fibrosarcoma cells, a mechanism involved in hypoxia-induced invadopodia production." (PMID 35681731, 2022).
granulosa cell tumor (3 papers, 2014 to 2024). A slow-growing, malignant tumor, characterize by the presence of granulosa-like cells and Call-Exner bodies, that is almost always found in the ovary. "Furthermore, genetic removal of SMAD3 expression from inhibin-α deficient mice leads to attenuated granulosa cell tumor progression and down-regulated CCND2 expression." (PMID 24416423, 2014). "Fang and colleagues emphasized that abnormal activation of SMAD3 might be a critical node of the canonical TGFbeta signaling in granulosa cell tumor development." (PMID 38806480, 2024). "Aberrant ovarian granulosa cell proliferation and apoptosis may lead to granulosa cell tumors (GCT), the pathogenesis of which involves transcription factors GATA4, FOXL2, and SMAD3." (PMID 24416423, 2014).
ischemia (3 papers, 2012 to 2023). A hypoperfusion of the BLOOD through an organ or tissue caused by a PATHOLOGIC CONSTRICTION or obstruction of its BLOOD VESSELS, or an absence of BLOOD CIRCULATION. "A recent study demonstrated that the VDR is involved in attenuating ischemia-induced oxidative stress and brain injury via reciprocal activation of SMAD family member 3 (SMAD3) and VDR transcription factors." (PMID 36831327, 2023). "Especially, SMAD3 and members of its family, transducting the signaling of TGF-β, are the important protective factor in ischemia/reperfusion." (PMID 23049867, 2012).
lymph node metastasis (3 papers, 2012 to 2020). "A further multivariable cox analysis (including sex, age, tumor grade, T stage, lymph node metastasis, miR-323a-3p expression, and SMAD3 expression) also confirmed the same result (P=0.047)." (PMID 28837140, 2017). "In our studies, we found a significant association of active TGFβ/Smad3 signaling, p21 and p/CAF expression with lymph node positivity, making them potential useful prognosis markers for lymph node metastasis." (PMID 22995475, 2012).
metastatic cancer (3 papers, 2017 to 2022). A carcinoma which has spread from the original site of growth to another anatomic site. "Pharmacological targeting of SMAD3 activity, such as with SIS3 (a specific inhibitor of SMAD3 C-terminal phosphorylation), was proposed as a potential therapeutic strategy to treat various diseases, including metastatic cancer." (PMID 35085106, 2022). "In addition, immunofluorescence staining analysis showed that crizotinib decreased the number of phospho-Smad3-positive cells in metastatic cancer tissues." (PMID 35999455, 2022). "Linker phosphorylation of Smad2 and Smad3 may represent a target for intervention in human metastatic cancer." (PMID 28471448, 2017). "Overall, TGFB1-mediated, EZH2-catalyzed SMAD3 K53/K333 methylation could function as a predictive marker of survival for patients with cancer and potentially serve as a therapeutic target for patients with metastatic cancer." (PMID 35085106, 2022).
oral squamous cell carcinoma (3 papers, 2020 to 2023). "A prior study has unveiled that GDF-10 through interaction with the transcription factor RUNX family transcription factor 2 can activate the TGFβRI/Smad3/ERK pathway in oral squamous cell carcinoma cells." (PMID 36714584, 2022). "Moreover, previous research demonstrated that miR-149-5p increased the chemosensitivity of cisplatin on oral squamous cell carcinoma via inhibiting TGF-β2, p-Smad2, and p-Smad3." (PMID 32982740, 2020).